AR (androgen receptor)
Diseases named in the same sentence as AR in open-access papers (continued):
Sharing a sentence is not in itself a finding about the gene and the disease.
prostate carcinoma (continued). "In conclusion, this study reported the synthesis and biological evaluation of a series of novel arylpiperazine derivatives against three human prostate cancer cells and human prostate epithelial cells and AR, respectively." (PMID 40224223, 2025). "AR, also known as NR3C4, is a nuclear receptor involved in various pathological processes, including Kennedy disease, Klinefelter syndrome, prostate cancer, and ovarian cancer." (PMID 40777854, 2025). "These miRNAs specifically target and suppress the expression of NKX3-1, leading to the dysregulation of the AR signaling pathway and driving the transformation of prostate cancer cells towards castration resistance." (PMID 41357241, 2025). "Speckle-type pox virus and zinc finger protein (SPOP) has emerged as a key focus in prostate cancer research due to its critical role in regulating the androgen receptor (AR) signaling pathway." (PMID 40432836, 2025). "KLK3 expression is regulated by androgens in prostate cancer, and androgen receptor signaling is known to be a key driver of both prostate and bladder cancer progression." (PMID 40427030, 2025). "CDK9 inhibition reduces aggressive prostate cancer cell growth by disrupting transcriptional elongation and AR-driven oncogenic programs and inhibits in vivo tumour growth." (PMID 40163908, 2025). "The AR, as the key driver in prostate cancer, can bind to SE regions to regulate the expression of downstream genes." (PMID 40470696, 2025). "The studies herein provide further evidence to support the biological importance of HSPs in advanced prostate cancer, demonstrating that both AR and AR-V7 bind members of the 70-kDa HSP family." (PMID 39787247, 2025). "This pro-oncogenic role extends to other malignancies: PELP1 acts as a co-activator for the androgen receptor (AR) in prostate cancer and promotes proliferation and metastasis in ovarian and pancreatic cancers." (PMID 41465416, 2025). "Nearly all primary prostate cancers are adenocarcinomas with AR expression and active androgen signaling, a core pathway in prostate cancer that promotes growth." (PMID 40493023, 2025). "It was designed and synthesised to degrade the androgen receptor (AR) and is used in the treatment of metastatic castration-resistant prostate cancer." (PMID 40430296, 2025). "The upregulation of cholesterol synthesis is conducive to the synthesis of endogenous androgens, which activate AR independently of exogenous androgens, thereby promoting the proliferation of prostate cancer." (PMID 39988626, 2025). "In contrast, AR/Sp1 formation on the cell surface type-A receptor 3 (EPHA3) promoter contributed to the expression of this gene which was induced by DHT in prostate cancer cell lines." (PMID 39858066, 2025). "Advances in treatment have introduced second-generation androgen receptor pathway inhibitors (ARPIs) as therapeutic options for prostate cancer across different clinical stages." (PMID 41134826, 2025). "FBS also contains physiologic levels of testosterone—10% FBS typically yields ~0.1 ng/mL testosterone in culture medium—which is sufficient to enhance proliferation of AR-positive prostate cancer cells and support AR-dependent tumor growth." (PMID 41463218, 2025). "Androgen receptor-positive prostate cancer cells abundantly express hormone-dependent tRNA halves, but their functions are unclear." (PMID 40471969, 2025). "For example, NAA10 is overexpressed in prostate cancer, where it promotes cell growth in vitro and tumor formation in vivo by acetylating the AR at lysine 618, leading to activation of AR target genes." (PMID 40558489, 2025). "The ethanolic extract P9605 and its major constituent cubebin selectively inhibit 5α-reductase type II and attenuate AR signaling, reducing proliferation in androgen-dependent prostate cancer cells." (PMID 41020902, 2025).
prostate carcinoma (continued). "AR antagonists lower MBOAT2 levels, and combining them with ferroptosis inducers potently suppresses tumor growth in AR+ prostate cancer." (PMID 41293165, 2025). "Fisetin, a dietary flavonol found in strawberries, apples, kiwis, and cucumbers, has been shown to inhibit AR signaling in prostate cancer cells by directly targeting AR-LBD region and disrupting the interaction between N-C terminals." (PMID 41020902, 2025). "We show that FZD6 is the most highly expressed and amplified frizzled receptors in both AR+ and AR- advanced prostate cancers." (PMID 41286306, 2025). "This integrated model of cistrome reprogramming and protein turnover reveals a key molecular circuitry by which prostate cancer cells escape AR dependency and adapt to hostile microenvironments." (PMID 40643528, 2025). "Studies suggest that NSUN2 and androgen receptor (AR) can establish a positive feedback loop in prostate cancer, accelerating disease progression." (PMID 40809690, 2025). "A recent publication inspected the relationship between YAP signaling and AR and discovered that YAP can inhibit the transcriptional program of AR in AR-positive prostate cancer." (PMID 40115748, 2025). "HT has shown selective cytotoxicity against prostate cancer cells compared to normal prostate cells by targeting the androgen receptor, which is essential for prostate cancer growth and progression, being a strength of this study." (PMID 40002421, 2025). "Advanced prostate cancer can initially be controlled with endocrine therapies that inhibit activity of the androgen receptor (AR), including androgen deprivation, the AR antagonist enzalutamide, and the androgen synthesis inhibitor abiraterone." (PMID 39847481, 2025). "Androgen receptor–mediated signaling plays a crucial role in prostate cancer progression, making it a key therapeutic target." (PMID 41092058, 2025). "Typically, prostate cancer cells depend on androgen receptor signaling to regulate differentiation and disease progression." (PMID 41465187, 2025). "Consistent with this, structured illumination microscopy in prostate cancer cells revealed signal-dependent nuclear enrichment of myosin VI, which localized in close proximity to AR as well as RNA Pol-II clusters and the actin nucleator DAAM2." (PMID 41443423, 2025). "The influence of CDK9 on AR pSer81 has been shown in both castration-sensitive and castration-resistant cell lines models of prostate cancer [,107]." (PMID 40163908, 2025). "This dual targeting of mitochondrial metabolism and androgen receptor signaling by Mito-LND strengthens its potential to enhance the efficacy of RT in prostate cancer." (PMID 39859224, 2025). "These AR antagonists work by binding competitively to the AR, thereby blocking the androgen-mediated process and inhibiting the proliferation of prostate cancer cells." (PMID 40017595, 2025). "In androgen receptor positive (AR+) prostate cancer, YAP impeded tumor growth by competing with AR for binding and TEAD-mediated signaling." (PMID 41347094, 2025). "Lineage plasticity is recognized as a critical determinant of lethality and resistance to AR pathway inhibitors in prostate cancer." (PMID 40454483, 2025). "By examining prostate cancer biopsies from patients treated with the AR pathway inhibitor (ARPI) enzalutamide, we previously found that a subset of tumors underwent lineage plasticity from AR-driven prostate cancer (ARPC) to DNPC." (PMID 40454483, 2025). "The activation of this AR signaling pathway effectively promotes the growth of prostate cancer cells." (PMID 40008000, 2025). "Although ARD-266 incorporates a VHL ligand with relatively weak binding affinity (Ki in the low micromolar range), it achieves potent Aryl degradation with DC50 values ranging from 0.2 to 1 nM in AR-positive prostate cancer cells." (PMID 40507351, 2025).
prostate carcinoma (continued). "It was demonstrated that the knockout of oncogene CDK12 in murine prostate cancer cells leads to the increased formation of R-loops through the upregulation of the androgen receptor (AR) and its coactivator FOXA1." (PMID 40725198, 2025). "Prostate cancer (PCa) is a significant public health issue, particularly in developed countries, where the androgen receptor (AR) plays a central role in both normal prostate development and cancer progression." (PMID 40781676, 2025). "Using confocal microscopy in a prostate cancer cell line expressing epitope-tagged AR and PARP7, we performed pixel-wise co-localization analysis." (PMID 40681873, 2025). "Recent studies have shown that the MAPK signaling pathway can promote prostate cancer progression by regulating androgen receptor (AR) signaling, and its abnormal activation is closely associated with drug resistance." (PMID 40044915, 2025). "AR mutations are known to be associated with resistance to ADT, and a previous study reported that AR mutations are detected in 10–30% of prostate cancer patients who progress to CRPC after ADT." (PMID 40660132, 2025). "Elevated expression of the AR is frequently observed in prostate cancer, resulting in increased activity." (PMID 41050263, 2025). "In contrast, in castration-resistant prostate cancer cells, AR-mediated signaling negatively regulates hTERT expression." (PMID 41301813, 2025). "Prostate cancer remains one of the most prevalent cancers in men, and while current hormone therapies aim to block androgen receptor activity, many patients eventually develop resistance, leading to advanced disease." (PMID 41374958, 2025). "Estrogen receptor (ER) and progesterone receptor (PR) pathways drive the majority of breast cancers, while androgen receptor (AR) signaling underpins the growth and progression of prostate carcinomas." (PMID 41228293, 2025). "Defining how these events are integrated with signal transduction is critical to understand how AR drives prostate cancer and unveil pathway features that are potentially amenable to therapeutic intervention." (PMID 40681873, 2025). "Prostate cancer grows in an androgen‐dependent manner, and the standard therapy for advanced prostate cancer is endocrine therapy targeting the androgen receptor (AR) signaling pathway." (PMID 40013333, 2025). "Previous studies have shown that miR-143 targets oncogenic pathways such as ERK/MAPK, PI3K/AKT, and androgen receptor signaling, all of which contribute to prostate cancer progression and drug resistance." (PMID 41446858, 2025). "Bioactivity tests with prostate cancer cells revealed that AA is an androgen receptor (AR) antagonist." (PMID 40072554, 2025). "For instance, FOXA2, by interacting with JUN, activates lineage plasticity enhancers, driving prostate cancer cells to transition from AR-dependence to a multilineage state." (PMID 40032852, 2025). "This article will focus on the molecular regulatory mechanisms of AR and the latest research progress in prostate cancer treatment." (PMID 40008000, 2025). "AR signaling has been a focal point for therapeutic interventions in prostate cancer, leading to the development of androgen deprivation therapy (ADT) as a cornerstone treatment for advanced disease." (PMID 40432836, 2025). "The most well‐established of these is androgen receptor (AR) signaling, promoting cell proliferation and survival in treatment‐naïve prostate cancer." (PMID 40493023, 2025). "In conclusion, this study demonstrates that LKB1 inactivation contributes to AR-independent lineage plasticity, DNA hypomethylation and antiandrogen resistance in prostate cancer." (PMID 39743630, 2025). "This inhibition prevents AR degradation, resulting in elevated AR levels in prostate cancer cells and promoting their survival through AR-mediated signaling." (PMID 40001982, 2025). "GLI3 and AR appear to cooperate in promoting androgen-independent growth in SPOP-mutant prostate cancer cells." (PMID 40432836, 2025).
prostate carcinoma (continued). "We observed that AR overexpression in VCaP‐oe‐HIC1 cells stimulated AR expression and enhanced the growth, proliferation, invasive ability, and stemness of prostate cancer cells." (PMID 41050263, 2025). "In short, there remains much to understand about the context-dependent relationship between MYC and AR; given the central role of these factors in prostate cancer, further research in this area is certainly warranted." (PMID 40163908, 2025). "AR activity in prostate cancer cells has been shown to activate the MAPK pathway as well as Src and to increase levels of cyclin D1 via a PI3K/mTOR-mediated mechanism." (PMID 40075623, 2025). "The AR gene showed a positive correlation with C1GALT1 expression not only in prostate cancer but also in other cancer types, including pancreatic, rectal, kidney‐clear cell, head and neck, thyroid, testicular, glioblastoma, melanoma, and liver cancers." (PMID 40548474, 2025). "The combination of AR inhibitors with ADT has been recommended as a first-line treatment in the guideline of the CSCO for prostate cancer." (PMID 40496458, 2025). "Although most mechanistic data on AR and immune suppression come from prostate cancer and other androgen-sensitive tumors, emerging studies in melanoma suggest a similar paradigm." (PMID 40940929, 2025). "We identified a post-transcriptional mechanism that regulates AR protein levels and gene expression in prostate cancer cells." (PMID 40681873, 2025). "The data showed that LLS30 inhibited the expression of AR target genes and androgen-induced genes that promote prostate cancer proliferation." (PMID 39941722, 2025). "Altogether, our findings uncover a regulatory axis whereby HIF1α negatively regulates FOXA1 protein stability in prostate cancer cells, thereby suppressing androgen receptor signaling and promoting hypoxia-responsive transcriptional programs." (PMID 40643528, 2025). "Bicalutamide is an androgen receptor antagonist used as an adjuvant in the treatment of prostate cancer." (PMID 40034971, 2025). "Drug discovery efforts targeting prostate cancer have focused on androgen deprivation therapy, androgen biosynthesis inhibitors, AR antagonists, AR degraders, and agents that disrupt N-terminal and C-terminal interactions." (PMID 41020902, 2025). "In summary, as a core molecular target in prostate cancer, AR plays an indispensable role in the occurrence, progression, and treatment resistance of the disease." (PMID 40008000, 2025). "As one of the most frequently diagnosed cancers in men worldwide, prostate cancer (PCa) is highly dependent on androgen receptor (AR) signaling for its development." (PMID 41247636, 2025). "Monoamine oxidase A (MAOA) plays a significant role in prostate cancer progression and AR signalling." (PMID 41249932, 2025). "Despite substantial mutational heterogeneity across patients, genetic and molecular alterations in prostate cancer are convergent onto dysregulated androgen receptor (AR) signaling." (PMID 41468516, 2025). "Histone ubiquitination, specifically at H2BK120 regulated by RNF20 and RNF40, plays a crucial role in the transcriptional regulation of AR target genes in prostate cancer." (PMID 40356745, 2025). "This review systematically explores the pathways of ROS generation in prostate cancer, their interaction with the androgen receptor signaling pathway, and the role of external factors such as obesity and aging in promoting ROS production." (PMID 40178629, 2025). "To examine the impact of HIC1/AR/IRS2 on the progression of castration‐resistant prostate cancer, we injected HIC1‐silenced cells (LNCaP‐sh‐HIC1) and a control group (LNCaP‐sh‐NC) labeled with fluorescence into the posterior lobe of the prostate." (PMID 41050263, 2025). "It inhibits AR-positive prostate cancer cell proliferative by competitively displacing radiolabeled androgens and downregulating AR mRNA and protein levels in a dose-dependent manner." (PMID 41020902, 2025).
prostate carcinoma (continued). "AR plays a pivotal role in the development and progression of prostate cancer and has therefore been extensively investigated as a therapeutic target in oncology." (PMID 40507351, 2025). "The AR‐expressing prostate cancer cell line, LNCaP, was used to assess AREluc reporter assay functionality." (PMID 40013333, 2025). "The vast majority of prostate cancer (PCa) tumors are androgen receptor (AR) positive adenocarcinomas at initial diagnosis." (PMID 40370549, 2025). "It is well established that the frequency of AR amplification increases as prostate cancer progresses, with reported rates ranging from 10% to 20% in castration‐resistant prostate cancer (CRPC) and 41%–52% in mCRPC." (PMID 40716035, 2025). "Considering that AR-independent and neuroendocrine-like prostate cancers are more likely to receive platinum treatment, our study specifically addresses the clinical and biological relevance of BIRC5/survivin in this disease context." (PMID 41304997, 2025). "While the AR has been extensively studied in prostate cancer, breast cancer, and other malignant tumors, research on its application in head and neck tumors remains scarce." (PMID 40729027, 2025). "Morphogenesis, proliferation and androgen receptor status Neuroendocrine differentiation in human prostate cancer." (PMID 40668272, 2025). "This phenomenon is especially notable in cancer varieties where there are potent targeted therapies for key growth pathways, such as AR‐driven prostate cancer, epidermal growth factor receptor (EGFR)‐mutant lung cancer, and BRAF‐mutant melanoma." (PMID 40013333, 2025). "Preclinical studies provide compelling evidence that these agents can effectively interrupt AR signaling, thereby suppressing prostate cancer growth." (PMID 41020902, 2025). "AR has a preeminent role in developing prostate cancer, and possibly bladder cancer, and the use of specific estrogens has shown promise in treating the disease." (PMID 40023399, 2025). "According to recent research, it is feasible to create PROTACs that specifically target GPCRs linked to cancer, such as the estrogen receptor (ER) in breast cancer and the AR in prostate cancer, leading to strong anti‐tumor effects in preclinical models." (PMID 40969301, 2025). "In prostate cancer, Cdk5 additionally targets the androgen receptor (AR), phosphorylating it at multiple sites to increase its stability and activity." (PMID 41369365, 2025). "Another study indicated that miR-193a-5p affects STAT3 and androgen receptor (AR) in prostate cancer." (PMID 40161373, 2025). "Originally studied in relation to castration-resistant prostate cancer progression, oncogene β-catenin and its activation of the Wnt pathway was shown to bind AR and enhance its transcriptional activity in prostate cancer cell lines." (PMID 40269952, 2025). "Alterations in the AR are commonly observed to occur in castration-resistant prostate carcinoma and documented to play causal roles in driving resistance to ADT and androgen receptor signaling inhibitor therapy." (PMID 40956611, 2025). "Adenocarcinoma accounts for 90–95% of the pathological staging of prostate cancer and is characterized by androgen receptor (AR) and prostate-specific antigen (PSA) expression." (PMID 39975592, 2025). "Others have previously shown that PAK6 phosphorylates MDM2 at the Ser186 and Thr158 sites, activating MDM2 to ubiquitinate the androgen receptor and inhibit tumor growth in prostate cancer cells." (PMID 40650306, 2025). "Conversely, the inhibition of CYP3A5 has been shown to suppress prostate cancer growth by increasing the nuclear translocation of the androgen receptor." (PMID 39754188, 2025). "Consistently, CRISPR-based dependency maps (DepMap) identify p300 as the most essential HAT in AR-driven prostate cancer, implying a pivotal role of p300/H2BNTac on prostate cancer cell viability." (PMID 41044247, 2025).